ENSG00000262302 (novel protein)
Gene: Protein-coding gene on chromosome 17 (7,246,829 to 7,262,089, reverse strand). Ensembl gene ENSG00000262302.
Genetic constraint (gnomAD): Missense variants: 78 observed, 114.73 expected, observed/expected ratio (o/e) 0.68, 90% interval 0.56 to 0.82. Synonymous variants: 48 observed, 47.17 expected, observed/expected ratio (o/e) 1.02, 90% interval 0.81 to 1.29.